ID4 (inhibitor of DNA binding 4)
Diseases named in the same sentence as ID4 in open-access papers (continued):
Sharing a sentence is not in itself a finding about the gene and the disease.
cancer (continued). "Detailed analyses indicated that Id4 could promote E-cadherin expression through the binding of Slug, cause the occurrence of mesenchymal-epithelial transition (MET), and inhibit cancer metastasis." (PMID 31847356, 2019). "In this study, we report that the expression of Id4 could attenuate cell migration and invasion in vitro and cancer metastasis in vivo." (PMID 31847356, 2019). "Since the expression levels of Id4 could interfere with cancer metastasis, the next aim was to understand how Id4 is involved in this complex process." (PMID 31847356, 2019). "Until now, the role of Id4 in cancer has remained ambiguous." (PMID 31847356, 2019). "Evidence showed that inhibition of ID4 contributes to developmental defects and cancer progression." (PMID 28452111, 2017). "In addition, it was reported that ID4 protein enhances the translation of mRNAs encoding pro-angiogenic cytokines, such as interleukin 8 and growth-regulated oncogene-α, and that ID4 increases the angiogenic potential of cancer cells." (PMID 25503067, 2015). "Thus epigenetic inactivation of ID4 due to promoter methylation appears to be the key mechanism in many cancers." (PMID 25115397, 2014). "Interestingly, Id4 staining was also observed in seemingly normal tubules (indicated by asterisk) adjacent to cancer." (PMID 23342267, 2012). "We present here an overview of the current experimental data that links Id4 to cancer." (PMID 21293053, 2010). "Id4 protein binds, stabilizes and enhances the translation of mRNAs encoding proangiogenic cytokines, such as IL8 and GRO-alpha, increasing the angiogenic potential of cancer cells." (PMID 21293053, 2010). "Nevertheless, the opposing functions of Id4 in cancer cells suggest that its molecular mechanism of action may depend on the genotype that may be permissive for its pro- or anti-neoplastic function." (PMID 19500415, 2009). "As we observed that ID4 expression in macrophages is strongly related to ID4 levels in BC cells, we wondered whether ID4 induction in macrophages depended on activation of the macrophage endogenous ID4 promoter or on the transfer of the ID4 mRNA/protein from cancer cells to macrophages." (PMID 32054109, 2020). "Therefore, ID4 may become an important index for judging the prognosis of tumors and a potential target for cancer therapy." (PMID 32328189, 2020). "Next, we assessed whether Id4 could inhibit cancer metastasis in vivo." (PMID 31847356, 2019). "These specific molecular mechanisms might interfere with the role of Id4 in cancer metastasis." (PMID 31847356, 2019). "As previously reported, the occurrence and progression of cancers includes both genetic and epigenetic alterations, and for epigenetic alterations, ID4 gene methylation could be used for auxiliary diagnosis and prognosis of MDS patients without significant genetic alterations." (PMID 25889027, 2015). "Thus, Id4 appears to exhibit unique regulatory functions in diverse cancer types." (PMID 19500415, 2009). "Therefore, even in cancers arising from the same organ such as the breast, Id4 may have opposing effects." (PMID 19500415, 2009). "ID4 was identified as a target of miR-668-3p through luciferase reporter and RIP assays, which was abnormal in different types of cancer." (PMID 35656024, 2022). "Comparing with pan-cancer driver genes, our study found that SIX1 was up-regulated, while TAL1 and ID4 were down-regulated in NSCLC." (PMID 31681566, 2019). "The interactions of HEY2 with Stat3 and Id4 that play important roles in tumorigenesis, also confirm the oncogenic role of HEY2 in human cancers." (PMID 27191260, 2016). "The data clearly indicates that ID4 functions as an inhibitor of extravasation in ELK3KD-231 cells, indicating that different ID proteins play distinct roles in coordinating the multiple factors in cancer cell metastasis." (PMID 38188675, 2023).
cancer (continued). "We did not detect the ID4-HA protein in macrophages, despite that ID4 mRNA was efficiently induced, indicating that the ID4 protein was not transferred from cancer cells to macrophages." (PMID 32054109, 2020). "Together, these results indicate that no ID4 protein or mRNA transfer occurred from cancer cells to macrophages." (PMID 32054109, 2020). "To rule out the possibility that the inhibitory effects of Id4 on cancer metastasis occurred through interfering with cell growth, we examined the effects of Id4 expression on cell proliferation and apoptosis in vitro and in vivo." (PMID 31847356, 2019). "In addition, SPHKAP was down regulated in cancer cell lines investigated, while the expression of DPP6 and ID4 was variable among cancer cell lines." (PMID 22479372, 2012). "In situ hybridization analysis of normal breast epithelium and carcinoma has shown that Id4 is expressed only in estrogen receptor negative (ER-) tissues." (PMID 21293053, 2010). "Furthermore, ID4/ VEGFA/ VEGFR2/ integrin β3 signaling stimulates the nuclear translocation and activation of the Hippo pathway member’s YAP and TAZ, two critical executors for cancer initiation and progression." (PMID 38321003, 2024). "Although our results consistently suggested that cancer invasion could be counter-regulated by Id4 and Slug, both in vitro and in vivo, such studies did not fully reflect clinical malignancy." (PMID 31847356, 2019). "ER-positive (ER+) cells are negative for Id4 expression both in normal epithelium and carcinoma." (PMID 21293053, 2010). "Furthermore, the extent of methylation was significantly greater in EAC compared to BE for six genes (CDKN2A, ID4, RBP1, RUNX3, SFRP1, and TMEFF2), suggesting that methylation of these genes occurs early in the progression of BE, with increased methylation as the disease advances toward cancer." (PMID 40149421, 2025). "However, the results presented here have uncovered an unexpected role for ID4 in the DNA damage response in BLBC, suggesting a similar dichotomy of function to BRCA1, that is, primarily regulating transcription during development whilst predominantly regulating the DNA damage response in cancer." (PMID 32527287, 2020). "There may be mechanisms other than LOH or methylation by which the wt BRCA1 allele is inactivated in BRCA1-associated cancers which were not examined in this study (for example, somatic mutation of the second allele elsewhere in the BRCA1 gene or ID4 modulation of BRCA1 expression)." (PMID 21080930, 2010). "Furthermore we have shown here that all ID proteins, except ID4, are expressed in cancer cell lines and that protein expression does not strictly correlate with mRNA expression, most likely due to post-translational modifications and/or ID protein stability and dynamics." (PMID 20070914, 2010). "Therefore, our data suggest that regulating AR activity indirectly through FKBP52 either by ID4‐ or by FKBP52‐specific inhibitors such as MJC13 would be a valuable pharmacological tool for selectively attenuating persistent AR activity in CRPC, irrespective of hormonal milieu of the cancer." (PMID 28252832, 2017).
adenocarcinoma (5 papers, 2008 to 2025). A common cancer characterized by the presence of malignant glandular cells. "However, ID2 and ID4 mRNA expression levels showed a favorable association with OS in adenocarcinoma." (PMID 32003423, 2020). "A recent report demonstrates that ID4 exerts antimetastatic activity in adenocarcinoma by promoting E-cadherin expression." (PMID 38188675, 2023). "The authors reported that ID4 interacts with Slug, a transcriptional repressor of E-cadherin, and sequesters it to increase E-cadherin expression; thus, ID4 induces mesenchymal-epithelial transition in adenocarcinoma." (PMID 38188675, 2023). "Methylation rates for ID4, DCL1, BNIP3, H2AFX, CACNA1G and TIMP3 were significantly different between squamous and adenocarcinomas." (PMID 20849603, 2010). "Among the novel methylated candidates identified, ID4, BNIP3, H2AFX, CACNA 1G, TGIF were more frequently methylated in squamous tumors, while HTLF and CACNA1A were commonly methylated in adenocarcinomas." (PMID 20849603, 2010). "Statistically significantly different methylation rates were observed for ID4-2 (p = 0.011), DCL1 (p = 0.019), BNIP3 (p = 0.003), H2AFX (p = 0.001), H2AFX-2 (p = 0.005), CACNA1G (p = 0.007) and TIMP3 (p = 0.021) when comparing squamous versus adenocarcinoma cases." (PMID 20849603, 2010).
infection (2 papers, 2010 to 2023). The state of being infected such as from the introduction of a foreign agent such as serum, vaccine, antigenic substance or organism. "Our work shed light on the impact of EBV infection by demonstrating strong downregulation of ID2 and ID4 upon infection." (PMID 21194482, 2010). "Some of the highly expressed genes (Log2 FC > 3.5) in inverse manner during Neisseria and Borrelia like HAPLN1, MT3, PITX2, ID4, ELAFIN, SLPI, etc., could be targeted to know their relevance in favoring or resisting the infection." (PMID 38179419, 2023). "EBV infection did not increase methylation of ID4 since its promoter was already largely methylated before infection occurred." (PMID 21194482, 2010).
hematological cancers (1 paper, 2015). "ID4 contributes to cell differentiation and proliferation, and abnormal methylation of the ID4 gene in hematological cancers plays an important role in diagnosis and prognosis." (PMID 25889027, 2015).
skeletal dysplasia (1 paper, 2024). Any Mendelian diseases that affects growth and development of the skeleton. "It was hypothesized that the 2 Mb deletions bring limb enhancers into close proximity with ID4 due to deletion of a topologically associated domain, resulting in the aberrant activation and misexpression of ID4 in the limb bud, and causing a skeletal dysplasia." (PMID 38397148, 2024).
ID4 also shares sentences with these, for which no sentence is quoted: acute myeloid leukemia (4 papers); esophageal adenocarcinoma (3); hepatocellular carcinoma (3); dysplasia (2); small cell lung carcinoma (2); adenoma (1); Amoebiasis (1); autoimmune disease (1); B-cell acute lymphoblastic leukemia (1); B-cell precursor acute lymphoblastic leukemia (1); breast adenocarcinoma (1); cardiomyopathy (1); cholangiocarcinoma (1); colorectal tumors (1); contact dermatitis (1); diabetes (1); eczema (1); ependymoma (1); familial cancers (1); gynecologic cancer (1); hematological malignancies (1); hypothyroidism (1); inflammatory skin disease (1); invasive ductal breast carcinoma (1); metastatic prostate carcinoma (1); multiple sclerosis (1); Myelodysplasia (1); non-small cell lung carcinoma (1); oligoastrocytoma (1); oligodendroglioma (1).
A further 12 diseases each share a sentence with ID4 in 1 paper.